DDR1 (discoidin domain receptor tyrosine kinase 1)
Diseases named in the same sentence as DDR1 in open-access papers (continued):
Sharing a sentence is not in itself a finding about the gene and the disease.
lung carcinoma (45 papers, 2007 to 2026). "DDR1 is a prognostic marker for non‐small cell lung cancer (NSCLC), and its upregulation is significantly associated with lymph node metastasis of NSCLC." (PMID 40105492, 2025). "One notable exception is lung cancer where KRAS mutations induce DDR1 expression to sustain Notch oncogenic signalling and tumorigenesis." (PMID 29438985, 2018). "DDR1 expression is higher in solid malignant tumors than in normal tissues, and elevated DDR1 expression has been associated with a poor prognosis in pancreatic and lung cancers." (PMID 28143619, 2017). "Knockdown of DDR1 in lung cancer cells and endothelial cells phenocopied the cells deficient of α5(IV)." (PMID 25992553, 2015). "This is the first study to show a strong association of the collagen binding RTK, DDR1 with human lung cancer." (PMID 17299390, 2007). "Low DDR1 expression tends to lead to a poor disease-free survival rate in triple-negative breast cancer patients and is associated with poor prognosis in lung cancer patients." (PMID 35004699, 2021). "The presence of mutations within DDR1 kinase domain in multiple cancers, such as non‐small cell lung cancer and acute myeloid leukemia, which may result in the resistance to small molecular inhibitors, has been reported." (PMID 31116512, 2019). "Finally, a previous study linked DDR1 to Notch signalling in lung cancer and Notch also acts as an oncogene in metastatic CRC." (PMID 29438985, 2018). "In this context, we recently discovered a novel functional cross-talk between IGF-IR and the collagen receptor discoidin domain receptor 1 (DDR1), a molecule also overexpressed in diverse malignancies, including lung carcinomas, and implicated in cancer progression." (PMID 27384677, 2016). "Assessment of Kaplan–Meier curves through immunohistochemistry revealed that high expression of DDR1 is an unfavorable prognostic marker in lung cancer." (PMID 40713963, 2025). "To investigate the role of DDR1 in lung cancer cell proliferation, invasion, migration, and adhesion, we performed siRNA-mediated knockdown of DDR1 in NSCLC cell lines." (PMID 41394854, 2025). "In this study, DDR1 was found upregulated during chemotherapy and its expression levels correlated with poor response to chemotherapy in lung cancer patients." (PMID 35936735, 2022). "Mounting evidence shows that DDR1 expression is significantly upregulated in a variety of cancers, including ovary, breast, colon, and lung cancers." (PMID 35935941, 2022). "The elevation of DDR1 expression was observed to be significantly correlated to poor prognosis in patients with lung cancer (OS HR = 1.26, p = 0.00042; FP HR = 1.44, p = 6e−04) and gastric cancer (OS HR = 1.41, p = 6.8e−05; PPS HR = 1.52, p = 0.00021)." (PMID 35935941, 2022). "On the contrary, DDR1 in tumor cells is important for the migration of lung cancer cells to the bone niche after intracardial injection." (PMID 33917302, 2021). "Collectively, these data support a potential cancer-protective function for DDR1 at least in breast and lung cancers." (PMID 35004699, 2021). "Opposed results were obtained by Valencia and cols using H460 lung carcinoma cells, indication that adhesion is a complex process as a result of multiple DDR1-dependent and independent pathways." (PMID 32090682, 2020). "DDR1 oncogenic role in human cancers was first highlighted by global phospho-tyrosine profiling in lung cancer." (PMID 32117772, 2020). "We report here that TM4SF1 regulates lung cancer chemo-sensitivity and apoptosis through the DDR1-activated AKT/mTOR signaling pathway." (PMID 31142317, 2019). "The authors further found that lung cancer cells with knockdown of DDR1 exhibited significantly decreased bone tumor burden." (PMID 31330786, 2019). "Here, we provide novel evidence regarding the molecular mechanisms through which IGF-I/IGF-IR signaling triggers a functional cross-talk with GPER and DDR1 in both mesothelioma and lung cancer cells." (PMID 27384677, 2016).
lung carcinoma (continued). "The promise of DDR kinases as a therapeutic target has been demonstrated by DDR1 knockdown that has been shown to reduce metastatic activity in lung cancer models, slow the development of atherosclerosis and impede the development of fibrotic disorders." (PMID 24768818, 2014). "We must therefore conclude that if these recently reported DDR1 and DDR2 mutations are valid, then their prevalence must be much lower in the general lung cancer population than expected." (PMID 17299390, 2007). "Increased DDR1 expression confers chemoresistance to ovarian and lung cancers." (PMID 40603853, 2025). "Our results demonstrated that DDR1 protein promotes t-DARPP expression in lung cancer cells." (PMID 38308500, 2024). "The findings presented herein show that DDR1 might exert some anti-tumorigenic effects in immunogenic lung cancer models." (PMID 38136314, 2023). "However, the authors discussed a tetraspanin TM4SF1-dependent mechanism of DDR1 upregulation, previously reported in lung cancer metastasis." (PMID 35936735, 2022). "This new DDR1 activity was corroborated in KRAS-mutant lung cancer upon treatment with platinum." (PMID 35936735, 2022). "Importantly, pharmacological DDR1 inhibition gave a synergistic effect with chemotherapy in a number of lung cancer experimental models tested." (PMID 35936735, 2022). "α5(IV) deficiency in lung cancer cells resulted in decreased expression of non-integrin collagen receptor discoidin domain receptor-1 (DDR1), and α5(IV) regulates cell proliferation via DDR138." (PMID 33558482, 2021). "In lung cancer, DDR1 inhibition decreases the activity of MMP2 and MMP9." (PMID 33917302, 2021). "Indeed, some mutations have been identified in DDR1 and DDR2 throughout their structures, but the impact of mutations has been studied mainly for DDR2 and more particularly in lung cancer." (PMID 33917302, 2021). "Lung cancer cells may express DDR1 when induced by collagen I in the bone, which completes its homing process." (PMID 33262947, 2020). "We addressed whether the expression of TMPRSS4 and DDR1 would be mutually regulated in lung cancer cells." (PMID 31659178, 2019). "Study of mesothelioma and lung cancer cells has also suggested that the collagen receptor discoidin domain 1 (DDR1)-mediated upregulation of connective tissue growth factor (CTGF) and early growth response 1 (EGR1) upon IGF-I stimulation requires both IGF-IR and GPER." (PMID 31708873, 2019). "We also addressed whether, like observed in lung cancer, DDR1 signalling is regulated by a RAS activity." (PMID 29438985, 2018). "Overall, on the basis of our data the multifaceted signaling network between IGF-IR, GPER and DDR1 could be taken into account in setting innovative combined strategies targeting these pathways in mesothelioma and lung cancers." (PMID 27384677, 2016). "Inhibition of DDR1 reduces cell survival, homing and colonization in lung cancer metastasis." (PMID 25992553, 2015). "DDR1 promotes metastasis through collective cell migration at the primary site and has been identified as a critical component for bone metastasis in lung cancer." (PMID 25369402, 2014). "Such inhibitors may have applications in clinical indications of DDR1 and DDR2 overexpression or mutation, including lung cancer." (PMID 24768818, 2014). "DDR1 was found to be overexpressed in breast, brain, colon, and lung cancers, thus suggesting that this receptor may play a role in the tumorigenesis of epithelial cancers." (PMID 21541037, 2011). "Moreover, high DDR1 expression was more frequently expressed in invasive carcinoma than in bronchioloalveolar carcinoma in lung cancers and was associated with shorter overall survival in non-small cell lung carcinomas." (PMID 35205677, 2022).
lung carcinoma (continued). "Similarly, DDR1 kinase activity is required for K-RAS-driven lung cancer and Notch tumor signaling." (PMID 32117772, 2020). "Moreover, in lung cancer, KRAS mutations induce DDR1 expression to sustain tumorigenesis." (PMID 32117772, 2020). "It shows that in patients with various cancer types, such as lung cancer, ovarian cancer, and PAAD, there is a significant occurrence of DDR1 gene amplification." (PMID 40869052, 2025). "We used a qRT-PCR approach with specific primers to amplify DDR1 and t-DARPP genes, which are important for lung cancer treatment." (PMID 38308500, 2024). "In A549 lung cancer cells, as collagen I does, the binding of IGF-1 to its receptor IGF-1R mediates DDR1-induced cell migration." (PMID 33917302, 2021). "DDR1 and GPER are both crucial to IGF-1-stimulated chemotactic motility in mesothelioma and lung cancer cells; this function is dependent on the formation of IGF-1-DDR1-GPER complexes." (PMID 31708873, 2019). "DDR1 is an up-stream regulator of the AKT/mTOR pathway, a pathway involved in chemo-resistance in multiple cancers, including lung cancer." (PMID 31142317, 2019). "In this study, we found that mesothelioma and lung cancer cells show a new complex functional cross-talk involving IGF-IR, GPER and DDR1, which affects gene expression and biological effects in response to IGF-I." (PMID 27384677, 2016). "In close accordance with these findings, we now show that the functional cooperation between IGF-IR and DDR1 also requires GPER, and that both DDR1 and GPER are critical to the chemotactic motility stimulated by IGF-I in mesothelioma and lung cancer cells." (PMID 27384677, 2016). "Through q-RT-PCR analysis, we found six genes (DDR1, HSP90B1, SDC1, RPSA, ERGIC3, and LPCAT1) significantly up-regulated and two genes (GPX3 and TIMP3) significantly down-regulated in the lung cancer tissues." (PMID 23374247, 2013). "In patients with idiopathic nonobstructive azoospermia or ovarian or lung cancers, DDR1 expression was found to correlate with the methylation of the promoter." (PMID 33917302, 2021). "In lung cancer cells, DDR1 knockdown has been reported to decrease ERK and Akt phosphorylation leading to a downregulation of cell proliferation suggesting a role of DDR1 autophosphorylation triggered by collagen IV binding in lung cancer progression." (PMID 32582700, 2020). "Altogether, these results indicate that, in both mesothelioma and lung cancer cells, IGF-I may up-regulate DDR1 target genes, and this action involves not only IGF-IR but also a cross-talk with GPER." (PMID 27384677, 2016). "Frederic Saltel's team proposed that DDR1 could be a sensor used by MDA-MB-231 breast and A549 lung carcinoma cells to interact with fibrillar type I collagen, leading to the organization of linear invadosomes, via a Cdc42-Tuba pathway." (PMID 27014069, 2016). "Knockdown of α5(IV) significantly decreased the expression of non-integrin collagen receptor DDR1 in lung cancer cells, which can be restored by ectopic mouse α5(IV) expression." (PMID 25992553, 2015). "α5(IV) signals through non-integrin collagen receptor DDR1 in lung cancer cells and endothelial cells." (PMID 25992553, 2015). "Similar to that in lung cancer cells, DDR1 expression was decreased in α5(IV)-, but not α1(IV)-, knockdown HMEC-1 cells." (PMID 25992553, 2015). "α5(IV), but not α1(IV), promotes lung cancer cell proliferation and tumor angiogenesis through non-integrin collagen receptor DDR1-mediated ERK activation." (PMID 25992553, 2015). "Co-activation of MET, AXL, ERBB2, and EPHA2, and co-activation of DDR1 with EGFR, DDR2, HCK, PDGFRA, and FGR is evidence that simultaneous activation of multiple tyrosine kinases may be common in lung cancer." (PMID 23300999, 2013). "We have conclusively shown that DDR1 is significantly more (2.15-fold) expressed in tumour as opposed to normal tissues from lung cancer patients, and have demonstrated that it can also be a strong prognostic indicator." (PMID 17299390, 2007).
lung carcinoma (continued). "Recently, it was shown that TM4SF1 can regulate AKT and ERK activation via DDR1 in lung carcinoma, but it is unclear whether or not these regulations require DDR1 tyrosine kinase activity and whether these pathways are involved in DDR1-induced colonization." (PMID 33917302, 2021). "Thus, minor Col IV α5(IV) chain supports lung cancer progression via DDR1-mediated cancer cell autonomous and non-autonomous mechanisms." (PMID 25992553, 2015). "Moreover, recent studies have highlighted that in lung cancer patients who are non-responders to treatment, there is an increased proportion of COL11A1+ tumor-associated fibroblasts (CAFs) that interact with tumor cells via the DDR1-collagen axis." (PMID 40713963, 2025). "However, DDR1 expression was not altered in α1(IV)-knockdown lung cancer cells." (PMID 25992553, 2015). "E xpression of the hub genes HBEGF, GJA4, DDR1, CD24, TBX2, GATA3, and SASH1 did not appear to be prognostic in lung cancer." (PMID 37324026, 2023). "α5(IV), but not α1(IV), ablation impaired expression of non-integrin collagen receptor discoidin domain receptor-1 (DDR1) and downstream ERK activation in lung cancer cells and endothelial cells." (PMID 25992553, 2015).
pancreatic cancer (32 papers, 2011 to 2025). "Previous reports associate upregulated DDR1 with increased metastatic potential in pancreatic cancer." (PMID 33233470, 2020). "Together, these results indicated that TM4SF1-induced invadopodia formation and function in pancreatic cancer cells were associated with the expression of DDR1." (PMID 28368050, 2017). "Collagen I, secreted by cancer-associated fibroblasts (CAFs), activates DDR1 on pancreatic cancer cells, enhancing macropinocytosis and mitochondrial biogenesis via the DDR1-NF-κB-NRF2 axis, and accelerating cell proliferation in vitro and tumor growth in vivo." (PMID 40563472, 2025). "In pancreatic cancer, the interaction between DDR1 and Transmembrane-4-L-six-family-1 (TM4SF1) increases the expression of MMP2 and MMP9, enzymes that degrade the basement membrane and disrupt tissue barriers, facilitating cancer cell invasion and metastasis." (PMID 40563472, 2025). "Cleaved type I collagen enhances macropinocytosis and mitochondrial biogenesis in pancreatic cancer cells via the DDR1-NF-κB-NRF2-TFAM axis." (PMID 40563472, 2025). "For example, discoidin domain receptor 1 (DDR1) was identified as a molecular target specific for pancreatic cancer." (PMID 39971899, 2025). "A recent animal model study demonstrated that the growth and metastasis of pancreatic cancer cells depend on Col-I cleavage that activates discoidin domain receptor 1 (DDR1) signaling." (PMID 39040062, 2024). "Targeting DDR1 reshapes the TME, inhibiting chemotherapy resistance induced by the ECM in pancreatic cancer through the DDR1/PYK2/FAK pathway." (PMID 38410129, 2024). "Combinations of DDR1 inhibitors and classical chemotherapeutics reduce tumor burden in orthotopic xenograft and orthotopic pancreatic cancer models." (PMID 37560476, 2023). "Our study confirmed activation of collagen-DDR1-mediated signaling promoted autophagic flux in pancreatic cancers and prolonged the survival of PDAC cells." (PMID 38071340, 2023). "Taken together, we conclude that collagen stimulates pancreatic cancer cells to produce CXCL5 through a DDR1/PKCθ/SYK/NF-κB pathway, and as a result, CXCL5 induces TANs to form NETs and promote cancer cell invasion and metastasis." (PMID 34237033, 2021). "To confirm this was a DDR1-mediated effect, we overexpressed DDR1 in an additional 5 human pancreatic cancer cell lines, which resulted in a significant increase of CXCL5 expression upon collagen activation." (PMID 34237033, 2021). "This is consistent with an in vitro study of pancreatic cancer cells which showed that DDR1 inhibits TGFβ1 expression, thereby promoting tumor cell proliferation." (PMID 33917302, 2021). "Taken together, these data suggest that DDR1 on pancreatic cancer cells induces the formation of NETs, which promote cancer cell invasion through an NAPDH oxidase-independent pathway." (PMID 34237033, 2021). "This gene is highly expressed in pancreatic cancer cells and stimulates metastasis by upregulating Discoidin Domain Receptor Tyrosine Kinase 1 (DDR1), Matrix Metallopeptidase 2 (MMP2) and Matrix Metallopeptidase 9 (MMP9)." (PMID 32000679, 2020). "The co-IP assays result and a positive correlation between TM4SF1 and DDR1 expression of pancreatic cancer tissues further provided the evidence of this interaction." (PMID 28368050, 2017). "We further analyzed and plotted TM4SF1 mRNA expression levels against the levels of DDR1 in pancreatic cancer tissue." (PMID 28368050, 2017). "Tks5, an adaptor protein required for invadopodia formation, was also used to investigate the role of TM4SF1 and DDR1 in pancreatic cancer cells." (PMID 28368050, 2017). "Both TM4SF1 and DDR1 are overexpressed in pancreatic cancer and related with metastasis development." (PMID 28368050, 2017). "These DDR1 inhibitors showed promising efficacy for pancreatic cancer treatment." (PMID 39971899, 2025). "However, blocking DDR1 signaling cascades by an SH2 superbinder inhibited collagen-induced autophagy in pancreatic cancer." (PMID 40025071, 2025).